IL2 (interleukin 2)
Diseases named in the same sentence as IL2 in open-access papers (continued):
Sharing a sentence is not in itself a finding about the gene and the disease.
melanoma (continued). "Notably, melanoma cells hinder the immune function of NK cells by suppressing their expression of NKG2D and NKp44, and given that IL-2 is considered necessary to render NK cells functionally competent upon NKG2D engagement, the IL-2-like effect of IK14004 on NK cells could be helpful." (PMID 40868162, 2025). "Furthermore, cytotoxicity by IL-2-activated peripheral blood lymphocytes was low in pigmented vs. non-pigmented melanoma, and lymphocyte-mediated killing effect was significantly increased by inhibition of melanogenesis by N-phenylthiourea or D-penicillamine (D-pen) sensitized melanoma cells." (PMID 35359389, 2022). "Generally, IFN-γ+ single cells might or might not coexpress IL-2 in melanoma specimens." (PMID 34321276, 2021). "HD IL-2 remains a viable treatment in melanoma and may be safely administered in a non-ICU setting." (PMID 28923120, 2017). "In this phase 1 trial, 17 patients with metastatic checkpoint inhibitor-resistant melanoma are treated with TILT-123 and TILs without preconditioning chemotherapy or postconditioning IL-2." (PMID 40107242, 2025). "CEL was shown to selectively and directly bind to IL‐2 but not CD25, thereby impairing IL‐2 and CD25 binding and exerting anti‐melanoma activity through the mediation of T‐cell responses." (PMID 40873643, 2025). "IFN-γ secretion in response to CSPG4+ A375M melanoma cells was enhanced in CAR T cells with engineered SLAMF6 release compared to control CAR T cells, while IL-2 release was not affected." (PMID 40558528, 2025). "Although, no trials were conducted to compare ipilimumab with interleukin-2 (IL-2), the magnitude of OS benefit seen with ipilimumab led to its approval for the adjuvant treatment of stage III melanoma." (PMID 30788189, 2018). "Encouraging results were also shown in another study by treating 57 patients with IV stage melanoma with unselected/young TIL and high-dose IL-2 following non-myeloablative lymphodepletion." (PMID 26217587, 2015). "Long-term survival was also demonstrated in a minority of patients with melanoma and RCC; however, no prospective randomized phase 3 studies have been performed with IL-2 showing a survival benefit." (PMID 24855563, 2014). "Adding further clinically-relevant variables (treatment assignment, prior Interleukin-2 usage, age, ECOG status or melanoma stage: all measured at baseline) did not result in significant coefficients or increase the predictive power of the model." (PMID 25214238, 2014). "For all patients with advanced melanoma, there is still an ongoing discussion about the best sequence to employ in the treatment of melanoma because of concerns that potential candidates for HD IL-2 may no longer be eligible for treatment due to complications from the preceding therapy." (PMID 23762555, 2013). "Additionally, the observed immunotherapy-like mixed responses and partial but durable responses coupled to the known lack of cytotoxicity of DAB/IL2 to human melanoma cells implies that the clinical activity of DAB/IL2 may rely in part on the known Treg-depleting effects of DAB/IL2." (PMID 22165955, 2011). "Like IL-2, IFNα is FDA approved, but only for adjuvant treatment of stage III melanoma patients and not for patients with metastatic disease." (PMID 21234353, 2010). "In contrast to the non-melanoma cells, transduction of melanoma M000301 and M21L4 cells gave rise to robust CD40L expression with both, AdTETP-IL-2/CD40L and AdTETP-CD40L/IL-2." (PMID 20670430, 2010). "Supernatant from CD8+ CTL793 after 24–48 hr of stimulation with autologous melanoma cells WM793 contained significant amounts of IFN-γ, TNF-α, and GM-CSF, but not IL-2 or IL-4 (data not shown, except for IFN-γ release in Table II)." (PMID 16281981, 2005). "In brief, before IL-2 exposure, there was a negative correlation between Fas and Bax expression in TIL from both melanoma and colon carcinoma, and a positive correlation between Fas and FasL only in TIL from colorectal carcinoma." (PMID 12610520, 2003).
melanoma (continued). "The frequency of IL-2+ cells within CD3+, CD4+, and CD8+ T cell populations significantly decreased after coincubation with human melanoma A375 cells regardless of IFN-γ pre-exposure (p < 0.05), while no significant change was seen after coincubation with Hermes 1 cells." (PMID 40574005, 2025). "Another consideration is whether the 14.18-IL-2 IC can be replaced with IL-2 alone or IL-2 + anti-GD2 mAb, to make this approach more clinically applicable for various cancers including GD2 negative melanomas." (PMID 37746303, 2023). "Similarly, in melanoma mouse models, treatment with NKTR-214 resulted in Treg number reduction in comparison to IL-2 without affecting CD8 and NK responses." (PMID 35891197, 2022). "The trials with IL-2/IFN and chemotherapy as neoadjuvant agents did not demonstrate a survival advantage, but they represent the basis for a promising neoadjuvant strategy in the treatment of stage III melanoma patients." (PMID 32708968, 2020). "Conspicuously, leukemia cells did not evoke IL-2 secretion from CSPG4-CAR T cells, whereas solid IL-2 secretion could be observed against melanoma cells." (PMID 31195686, 2019). "Interestingly, in a murine preclinical model of melanoma where anti-CTLA4 treatment alone was not efficient, a combination of IL2 superagonist and anti-CTLA4 led to reduced tumor growth and this effect was abolished when NK cells were depleted." (PMID 31614774, 2019). "A condition mimicking uveitis, an autoimmune reaction in the retinal pigment epithelium and the choroid of the eye, was reported in some melanoma patients undergoing immunotherapy with tumor-infiltrating lymphocytes plus IL-2, anti-CTLA-4 antibodies plus IL-2 with or without a gp100 vaccine." (PMID 27071457, 2016). "Although IL-2/JES6 has not been extensively tested in tumor models due to its biased expansion of Treg cells, we recently showed that IL-2/JES6 considerably improved doxorubicin-based chemotherapy in the mouse syngeneic B16F10 melanoma and BCL1 leukemia models." (PMID 40789741, 2025). "We also evaluated the protein amount of a set of 12 cytokines and chemokines, including IL-2, IL-4, IL-5, IL-6, IL-10, IL-12, IL-17A, TNF-α, IFN-γ, MCP-1, MIP-1α, and eotaxin in TIF and plasma samples of C57BL6 mice, engrafted or not engrafted with B16 melanoma cells." (PMID 34604232, 2021). "Powell and coworkers have performed a highly sophisticated trial in melanoma patients where non-myeloablative chemotherapy was combined with an infusion of in vitro-stimulated, gp100 peptide-reactive, autologous PBMC, high-dose IL-2 therapy and vaccination with gp100:209–217(210 M) peptide." (PMID 17868452, 2007). "However, in our study, we showed that inhibition of IFN-γ secretion itself could also contribute to abnormal STAT1 activation in melanoma patients, because STAT1 was not directly phosphorylated by IL-2 signaling, but depended on IFN-γ released by NK and T lymphocytes when stimulated with IL-2." (PMID 27153543, 2016).
COVID-19 (685 papers, 2020 to 2026). A disease caused by infection with severe acute respiratory syndrome coronavirus 2. "Co-infection also triggered robust increases in IFN-γ and IL-1β, whereas malaria alone was associated with higher IL-6, IL-4, and IL-10, and COVID-19 alone was associated with elevated IL-2 and TNF-α." (PMID 41758897, 2026). "This inflammation, driven by pro-inflammatory cytokines (interleukin-6 (IL-6), IL-1, IL-2, IL-10, tumour necrosis factor alpha, interferon-γ) and coagulation dysfunction, is thought to be the main cause of COVID-19-associated myocarditis." (PMID 40502868, 2025). "An ongoing clinical trial is currently assessing the efficacy of low-dose IL-2 therapy for COVID-19-associated acute respiratory distress syndrome (ARDS)." (PMID 40806563, 2025). "Six genes, including TNF, CXCL8, IL-6, IL-1β, IL-2, and IL-10, were associated with three major signaling pathways: the COVID-19 adverse outcome pathway, an overview of pro-inflammatory and pro-fibrotic mediators, and the interleukin-10 signaling pathway." (PMID 40166075, 2025). "COVID-19 severity is linked to elevated levels of inflammatory mediators, including cytokines (e.g., IL-2, IL-7, IL-10, IFN-γ, and TNF-α) and chemokines (e.g., G-CSF, MCP1, MIP1α, and CXCL10), as well as markers like C-reactive protein, ferritin, and D-dimers." (PMID 40649865, 2025). "Inflammation in COVID-19 is predictive of mortality and is associated with increased plasma concentrations of several cytokines including IL-2, IL-6, IL-7, IL-10, and TNF-α." (PMID 39345212, 2024). "Severe COVID-19 is associated with a cytokine storm characterized by elevated plasma concentrations of interleukins (IL-1ß, IL-2, IL-6, IL-7, IL-8, IL-10 and IL-17), interferons, monocyte chemoattractant protein 1 (MCP-1) and TNF-alpha." (PMID 38732160, 2024). "Of the 105 cytokines profiled in this study, nine were previously reported to be involved in the cytokine storm associated with COVID-19 including the following: IL-2, IL-4, IL-6, IL-10, G-CSF, IP-10, MCP-1, TNF-α, and IFN-γ." (PMID 39062978, 2024). "In severe COVID-19 patients, the hyperinflammatory response, also called the cytokine storm, is a hallmark feature with elevated circulating levels of IL-2/4/6/10, STAT1/2/3, and TNF-a." (PMID 38257800, 2024). "Age ≥ 60 years and BMI ≥ 30 kg/m2 at COVID-19 onset were associated with higher levels of IL2 and IP10, and MCP1 and CRP, respectively, when adjusting for other covariates." (PMID 39008486, 2024). "This is consistent with previous data that have shown that, in particular, IL-10 and IL-2 levels are higher in COVID-19 patients and associated with disease severity." (PMID 37175392, 2023). "Acute COVID-19 was associated with marked elevations in nearly all pro-inflammatory markers, whilst eleven markers (namely IL-1β, IL-2, IL-6, IL-10, IL-18, IL-23, IL-33, TNF-α, IP-10, G-CSF and YKL-40) were associated with disease severity." (PMID 37063871, 2023). "Cardinal markers of this syndrome are IL-2,6,7, ferritin, and some others, which are associated with COVID-19 severity and AKI incidence." (PMID 37238917, 2023). "COVID-19 mRNA vaccines are known to initiate Th1-biased immune responses associated with increased levels of IL-2, IFN-γ, and TNF, as well as CD4+ and CD8+ T-cells." (PMID 36851087, 2023). "Our findings confirm a defined cytokine signature in severe COVID-19 (with elevated IL-2, IL-6, TNFα, IL-1β and IL-10), and add further evidence to the role of IP-10, G-CSF and IL-33 in the cytokine milieu associated with severe COVID-19." (PMID 37063871, 2023). "In humans, abundant CD4+CD154+ T cells are associated with severe COVID-19, particularly in T cells producing abundant proinflammatory cytokines, including interferon-γ (IFNγ), tumor necrosis factor, interleukin-2 (IL-2) and/or interleukin-21 (IL-21)." (PMID 37856551, 2023). "IL-12 and IL-2 levels are increased in COVID-19 patients but their association with disease severity is controversial." (PMID 37998327, 2023).
COVID-19 (continued). "Patients with Major Depressive Disorder (MDD) are more likely to have elevated levels of TNF-, one of the three principal mediators of inflammation caused by the COVID-19 vaccinations, whereas elevated levels of IL-2 and IFN- are connected to depression." (PMID 36851087, 2023). "We found diverse signaling pathways and activation pathways associated with COVID-19 subsets, which were enriched in IL2/STAT5, PDGF, and mTOR signaling." (PMID 36992700, 2023). "In these studies, critical COVID-19 outcomes, extended hospitalization and lymphopenia in COVID-19 patients, and poor prognosis and disease severity were associated with a significant increase in IL-2 cytokine family profile, including IL-2, IL-4, and IL-15." (PMID 37649897, 2023). "It is worth mentioning that out of all the cytokines mentioned, IL-6 and IL-2 are strongly associated with the severity of the disease, meaning that they are more elevated in critically ill COVID-19 patients than in ordinary COVID-19 patients." (PMID 36295093, 2022). "Severe COVID-19 is known to cause a cytokine storm, in which over-activated lymphocytes secrete many cytokines such as interleukins (ILs); (IL2, IL6, IL7, etc.), and tumor necrosis factor (TNF)." (PMID 35615724, 2022). "In the case of COVID-19, it has been proposed that circulating sIL-2R causes lymphopenia by blocking IL-2 signalling." (PMID 35458517, 2022). "Elevated serum levels of IL-6, IL-8, IL-1β, and TNF-α correlate with moderate and severe COVID-19, while IL-12p70 and IL-2 serum expression is associated with asymptomatic and mild diseases." (PMID 36526691, 2022). "It has been reported that GGO correlates with cytokine levels, particularly those of IL-2, which support the spread of lesions in the lungs associated with a cytokine storm in COVID-19." (PMID 36327268, 2022). "It is currently acknowledged that severe forms of COVID-19 are associated with the release of cytokines, such as IL-2, IL-6, IL-7, IL-10, tumor necrosis factor (TNF), and granulocyte colony-stimulating factor (GCSF)." (PMID 35743583, 2022). "This body of evidence makes it feasible to think that subjects with a low number of IL-2-producing CD4+ T cells in response to in vitro polyclonal stimuli display increased susceptibility to severe COVID-19 after SARS-CoV-2 infection." (PMID 35860236, 2022). "The pattern linked to severe COVID-19 is characterized by high PD-1 expression, low IL-2 and IFN-gamma production in CD4+ and CD8+ T cells, and poor IFN-alpha expression in classical and non-classical monocytes." (PMID 35860236, 2022). "The IL-2/INF-γ ratio was the strongest indicator of a critical course of COVID-19 and was associated with fatal outcomes." (PMID 35891232, 2022). "Our study suggests that the initial frequency of IL-2-secreting cross-reactive T cells is associated with protection from infection in COVID-19 contacts." (PMID 35013199, 2022). "Two studies also found an association of increased levels of IL-2 and sIL-2R with mortality from COVID-19, and in another, a high sIL-2R/lymphocyte ratio proved to be the best indicator of critical disease differentiation." (PMID 34575258, 2021). "As another example, monitoring of COVID-19-associated CRS patient cytokine profiles in 2019 revealed higher levels of IL-2, IL-7, IL-10, G-SCF, MCP-1, MIP-1α, and TNF-α in plasma of intensive care unit (ICU) patients versus plasma of non-ICU patients." (PMID 34884813, 2021). "The association of the duration of illness of COVID-19 with circulating sIL-2Rα and IL-8 also provides supportive evidence for therapeutics targeting IL-2 and IL-8 singling pathways." (PMID 33584733, 2021). "We found that the IL-2/INFγ ratio was the strongest indicator of a critical course of COVID-19, and was associated with fatal outcomes." (PMID 34071149, 2021). "Our subsequent multivariate logistic regression analysis showed that IL-2 was a significant and independent risk factor for GGOs patients with moderate or severe COVID-19." (PMID 33967617, 2021).
COVID-19 (continued). "It is currently admitted that severe forms of COVID-19 are associated with a release of cytokines and chemokines such as IL-2, IL-6, IL-7, IL-10, tumor necrosis factor (TNF), and granulocyte colony-stimulating factor (GCSF)." (PMID 34552938, 2021). "Baricitinib inhibits the intracellular signaling pathway of cytokines implicated in severe COVID-19, including IL-2, IL-6, IL-10, IFN-γ, and granulocyte-macrophage colony-stimulating factor (GM-CSF)." (PMID 34063964, 2021). "Further, inflammatory dysregulated IL-2, IL-6, IL-10 and IL-15 are associated with COVID-19-related mortality." (PMID 34117221, 2021). "In COVID-19 patients, a profile of cytokines, such as IL-2, IL-6, IL-7, INF-γ, and TNF-α, is associated with disease severity and mortality of patients." (PMID 33679608, 2020). "On the other hand, asthma, a risk factor for adverse outcomes in COVID-19, is linked to IL-8, IL-5, IL-2, IFNg, eosinophils, and neutrophils." (PMID 32746922, 2020). "Symptoms of severe COVID-19 have been associated with a cytokine storm with high levels of IL-17, IL-10, IL-1β, IL-2, IL-7, IL-8, IL-9, among many other pro-inflammatory cytokines." (PMID 33071815, 2020). "A cytokine profile resembling sHLH is associated with COVID-19 disease severity, characterized by increased IL-2, IL-7, GCSF, IP-10, MCP-1, and MIP-α." (PMID 32983152, 2020). "In one of the very first reports of the clinical course of COVID-19 patients, as early as March 2020, serum increase in interleukin (IL)-2, IL-7, GMCSF, IP-10, MCP 1, MIP1-α, and TNF-α was associated to disease severity." (PMID 33019628, 2020). "Furthermore, when linking brain structural imaging with immunological markers, we observed a correlation between BMI-related GMV alterations and IL-8 and IL-2, respectively, both of which have previously been linked to COVID-19 severity and prognosis." (PMID 41323348, 2025). "In our study, we described the demographical and clinical characteristics of patients with COVID-19 stratified by severity and assessed associations to infer the potential use of inflammatory cytokines (IL-2, IL-4, IL-6, IL-8, IL-10, TNF-α, GM-CSF, and IFN-γ) as biomarkers of COVID-19 pneumonia." (PMID 40508859, 2025). "This Th1/IL-2-driven profile is frequently associated with effective immunity: in COVID-19, convalescent patients with favorable outcomes exhibit polyfunctional CD4+ T cells secreting IL-2, IFN-γ, and TNF-α, whereas severe cases often show loss of this functionality." (PMID 41357245, 2025). "To explore the mechanisms of decreased expression of PD-1 in CD4+ and CD8+ T cells from convalescent COVID-19 patients, we measured plasma cytokines associated with PD-1 expression, including IL-2, IL-6, IL-7, IL-10, IL-12p70, IL-33, IFN-γ and CCL19/MIP-3, by Luminex." (PMID 38424104, 2024). "We hereby displayed that PLWH with acute COVID-19 feature a distinct plasma cytokine profile (with higher Th1/Th2/Th17-like cytokines, yet lower IL-2 and IL-9), which, in turn, is associated with poorer control of SARS-CoV-2 replication/dissemination and worse respiratory insufficiency." (PMID 38188525, 2024). "There is limited research on the role of IL-2 in different COVID-19 variants." (PMID 37649897, 2023). "Furthermore, COVID-19 caused excessive production of proinflammatory cytokines such as IL-6, IL-2, IL-7, granulocyte-colony stimulating factor (G-CSF), Macrophage Inflammatory Protein-1 Alpha ((MIP-1-α)/CCL3, and TNF-α), termed as cytokine storm." (PMID 37377785, 2023). "In addition to the CD8+ T-cell defect, CD4+ T cells in COVID-19 cases also express the exhausted markers, and a high frequency of non-functional CD4+ T cells that are deficient at producing IFNγ, IL-2, and TNFα has been demonstrated in severe COVID-19 cases." (PMID 36839573, 2023). "High levels of cytokines, such as IL-2, IL-1b, and IL-10, may be associated with thrombotic complications in patients with COVID-19." (PMID 37112918, 2023).